INTS2 (integrator complex subunit 2)
Description:
Component of the integrator complex, a multiprotein complex that terminates RNA polymerase II (Pol II) transcription in the promoter-proximal region of genes. The integrator complex provides a quality checkpoint during transcription elongation by driving premature transcription termination of transcripts that are unfavorably configured for transcriptional elongation: the complex terminates transcription by (1) catalyzing dephosphorylation of the C-terminal domain (CTD) of Pol II subunit POLR2A/RPB1 and SUPT5H/SPT5, (2) degrading the exiting nascent RNA transcript via endonuclease activity and (3) promoting the release of Pol II from bound DNA. The integrator complex is also involved in terminating the synthesis of non-coding Pol II transcripts, such as enhancer RNAs (eRNAs), small nuclear RNAs (snRNAs), telomerase RNAs and long non-coding RNAs (lncRNAs). Mediates recruitment of cytoplasmic dynein to the nuclear envelope, probably as component of the integrator complex.
Synonyms: Int2; KIAA1287
Tractability: Antibody: UniProt predicts a signal peptide or a membrane-spanning region. PROTAC: ubiquitination databases record sites on it; its protein half-life has been measured.
Gene: Protein-coding gene on chromosome 17 (61,865,367 to 61,928,016, reverse strand). Ensembl gene ENSG00000108506.
Subcellular location: Nucleus; Nucleus membrane; Cytoplasm
Pathways (Reactome):
Gene expression (Transcription): RNA polymerase II transcribes snRNA genes
Gene Ontology:
Molecular function: protein binding
Biological process: regulation of transcription elongation by RNA polymerase II; RNA polymerase II transcription initiation surveillance; snRNA processing; snRNA 3'-end processing
Cellular component: cytoplasm; INTAC complex; integrator complex; membrane; nuclear membrane; nucleus; nucleoplasm
Genetic constraint (gnomAD): Loss-of-function variants: 27 observed, 75.87 expected, observed/expected ratio (o/e) 0.36, 90% interval 0.26 to 0.49. The upper end of that interval is the gene's LOEUF score, 0.49, which puts it in group 2 of 6, group 1 being the genes least tolerant of losing a copy. Missense variants: 771 observed, 958.7 expected, observed/expected ratio (o/e) 0.8, 90% interval 0.76 to 0.85. Synonymous variants: 332 observed, 342.17 expected, observed/expected ratio (o/e) 0.97, 90% interval 0.89 to 1.06.
Homologues: Orthologues: chimpanzee INTS2 (99% identical), macaque INTS2 (99% identical), dog INTS2 (98% identical), guinea pig INTS2 (98% identical), rabbit INTS2 (97% identical), mouse Ints2 (96% identical), rat Brip1 (96% identical), pig INTS2 (91% identical), tropical clawed frog ints2 (83% identical), zebrafish ints2 (79% identical), Drosophila melanogaster IntS2 (37% identical), Caenorhabditis elegans ints-2 (19% identical).
Diseases named in the same sentence as INTS2 in open-access papers:
INTS2 is named in the same sentence as 4 diseases in open-access papers, as found by Europe PMC text mining. Sharing a sentence is not in itself a finding about the gene and the disease. The quoted sentences say what the papers report.
gastric cancer (1 paper, 2024). A primary or metastatic malignant neoplasm involving the stomach. "A GWAS screening identified the INTS2 mutation (p.G906K) in gastric cancer peritoneal carcinomatosis." (PMID 38926181, 2024).
hepatocellular carcinoma (1 paper, 2016). A malignant tumor that arises from hepatocytes. "Interestingly, by searching for the TCGA mutation data, we found a hepatocellular carcinoma patient harboring the INTS2 recurrent mutation (G906K)." (PMID 26811494, 2016).
cancer (2 papers, 2019 to 2023). A tumor composed of atypical neoplastic, often pleomorphic cells that invade other tissues. "The under-expressed HEG1 encodes protein participating in the cancer metastasis process, while the protein encoded by the downregulated INTS2 belongs to a key regulator of RNA polymerase II-mediated transcription integrator complex." (PMID 37894381, 2023). "INTS2 and INTS8 are also miss-expressed or mutated in many cancers." (PMID 31311534, 2019).
INTS2 also shares sentences with these, for which no sentence is quoted: tumor (2 papers).